SOX13 (SRY-box transcription factor 13)
Diseases named in the same sentence as SOX13 in open-access papers (continued):
Sharing a sentence is not in itself a finding about the gene and the disease.
bipolar disorder (1 paper, 2022). A disorder of the brain that causes unusual shifts in mood, energy, activity levels and the ability to carry out day-to-day tasks. "Other regulated genes by Sox13 might be associated to PD syndrome; for example, Nckap5 is considered the most promising candidate for bipolar disorder, and Epb41l2 gene is associated with cognitive impairment in the hippocampus induced by anesthesia." (PMID 36142685, 2022).
brain tumors (1 paper, 2020). "SOX6 and SOX13 could co-interact with FOXC1 and GATA2, which might lead to aggressive the brain tumors." (PMID 32388501, 2020).
influenza (1 paper, 2024). An acute viral infection of the respiratory tract, occurring in isolated cases, in epidemics, or in pandemics; it is caused by serologically different strains of viruses (influenzaviruses) designated A, B, and C, has a 3-day incubation period, and usually lasts for 3 to 10 days. "Zanamivir (T2529 in the compound library), the first neuraminidase inhibitor approved for the prevention and treatment of influenza, had the lowest KD values (6.87×10-6) for SOX13 protein." (PMID 38769295, 2024).
liver cancer (1 paper, 2024). An epithelial or non-epithelial malignant neoplasm that arises from the liver. "Emerging reports have indicated high SOX13 levels in liver cancer, with links to both metastasis and unfavorable prognosis." (PMID 39726600, 2024).
lung squamous cell carcinoma (1 paper, 2023). "SOX13 accounted for 22% of the high-risk variants in lung squamous cell carcinoma, SOX 2 for 33% of pancreas ductal carcinoma, and SOX7 for 40% of thyroid NS cancer." (PMID 36672963, 2023).
prostate carcinoma (1 paper, 2014). A carcinoma that arises from epithelial cells of the prostate gland. "By inspection, we also identified at least 10 additional transcription factors within 500 kb of 9 other GWAS loci, that are also reasonable candidates for contributing to prostate cancer risk: SOX13, ZFP36L2, ATOH8, DLX1 & DLX2 (same locus), GATA2, SKIL, SP8, ASCL2, and DPF1." (PMID 24497837, 2014).
cancer (18 papers, 2013 to 2024). A tumor composed of atypical neoplastic, often pleomorphic cells that invade other tissues. "The results indicated that SOX13 was positively correlated with cancer-associated fibroblasts, endothelial, M2 macrophage, etc., and negatively correlated with CD8+ T cells, myeloid dendritic cells, monocytes, etc. in BRCA." (PMID 38707897, 2024). "Conversely, the circRNAs encoded by CHST15, WDR37, and SOX13, and their role in cancer have been previously delineated in the literature." (PMID 37106694, 2023). "Overall, these reports indicate that SOX13 has tumor-associated functions in multiple cancer types." (PMID 39726600, 2024). "Combining with the SOX13 expression and its drug sensitivity analysis, we may establish risk stratification for cancer patients, which optimizes the development and application of anti-cancer drugs." (PMID 38707897, 2024). "And the results showed that the upregulation of SOX13 could maintain cancer stem-like properties in HCC cells and was associated with the poor differentiation, metastasis, and recurrence of HCC patients." (PMID 35465267, 2022). "Notably, the function of SOX13 is associated with cancer development." (PMID 39872660, 2024). "Within the SOXD subfamily, SOX13 was the most closely related to cancer development and progression." (PMID 39726600, 2024). "To assess the SOX13 expression in human cancers, we verified the different expression between the adjacent normal tissues and tumor for SOX13 across all TCGA tumors by TIMER database." (PMID 38707897, 2024). "The transcript level of SOX13 positively correlates with that of SCAF1 in multiple cancers, including GC, based on the databases TIMER and GEPIA." (PMID 38769295, 2024). "The present findings demonstrated that high expression of SOX13 negatively relates to prognosis and SOX13 plays an important role in cancer immunity." (PMID 38707897, 2024). "SOX13 has been revealed to be an essential regulatory element for cell differentiation and cell stemness in both normal and cancer tissues via the regulation of Wnt/β-catenin signaling." (PMID 38707897, 2024). "These SOX genes, namely SOX5, SOX6, and SOX13, demonstrate diverse roles in embryonic development and cancer biology." (PMID 38132479, 2023). "As a widely reported transcription factor, SOX13 affects cell migration, invasion, and angiogenesis in various cancers and plays a role in an oncogene." (PMID 35769464, 2022). "SOX13 has also been studied in various cancers where many functions are related to stem cell fate determination." (PMID 36247423, 2022). "Then, immunohistochemical analysis was employed to prove that the protein level of SOX13 was increased in tumor tissues compared with para-carcinoma tissues (***p < 0.001)." (PMID 35611828, 2022). "We analyzed SOX13 expression across 38 cancer types using the TIMER2.0 database." (PMID 39726600, 2024). "Such dataset outcomes imply that SOX13 could be a prognostic biomarker within numerous cancers, including THCA." (PMID 39726600, 2024). "According to a previous study, SOX13 could promote cancer cell proliferation, migration, and chemoresistance." (PMID 39872660, 2024). "First, analysis in the cBioportal database showed the alteration frequency of SOX13 in Pan-cancer." (PMID 38707897, 2024). "Considering the important role in ferroptosis-related therapeutic efficacy, SOX13 might be an attractive anti-cancer drug target." (PMID 38769295, 2024). "In addition, SOX13 strongly regulates cancer immunity and Ferroptosis." (PMID 39726600, 2024). "Presently, cancer angiogenesis research is mainly focused on VEGF, but some studies have identified that circRNA can regulate cancer angiogenesis via AGGF1, ZIC4, and SOX13." (PMID 37616050, 2023). "SRY-BOX13 (SOX13) as a crucial member of SOX family has been proved to exert essential role in regulating normal and cancer cell properties by mediating Wnt/β-catenin signaling pathway." (PMID 35611828, 2022).
cancer (continued). "Also, SOX13 contributes to control Wnt/TCF activity, crucial in HCC pathogenesis and cancer stem cell renewal." (PMID 24160375, 2013).
tumor (14 papers, 2013 to 2026). "As a tumor biomarker with diagnosis and treatment potential in various tumors, high SOX13 expression is linked to poor prognosis." (PMID 38707897, 2024). "This investigation revealed that SOX13 levels within tumor samples were markedly associated to tumor status and pathological phase, as well as survival outcomes." (PMID 39726600, 2024). "Associations between these parameters were examined by univariate analysis, finding a significant association between reduced SOX13 levels and T and pathological stage, and histological and primary neoplasm focus types (all P< 0.05)." (PMID 39726600, 2024). "Whereas PD1 antibody-targeted monotherapy moderately inhibited the growth of tumors from wild-type YTH16 (m) xenografts, anti-PD1 antibody monotherapy caused a more pronounced suppressive effect on tumor growth in tumors from YTH16 (m) cells with SOX13 knockout." (PMID 38769295, 2024). "Therefore, herein, we investigated the association between SOX13 and tumor immunity, with the goal of determining its potential as an immunotherapy target." (PMID 39726600, 2024). "In addition, reduced SOX13 content was linked with worse patient prognosis and advanced tumor stages." (PMID 39726600, 2024). "Furthermore, results obtained from xenograft tumor model demonstrated that silencing SOX13 significantly inhibited the tumor growth in vivo and reduced TRIM11 and glycolysis-associated proteins expression." (PMID 35611828, 2022). "The expression of SOX13 is high in numerous solid types of tumor, including hepatocellular carcinoma, colorectal cancer, and gastric cancer." (PMID 38707897, 2024). "Here, we identified an association between infiltration and SOX13 levels, observing that SOX13 was negatively associated with the numbers of cytotoxic, regulatory T cell, and B cells in THCA tumor samples." (PMID 39726600, 2024). "Further, the expression of SOX13 was also confirmed to be correlated with tumor microenvironment and diverse infiltration of immune cells." (PMID 38707897, 2024). "SOX13 showed significant discreet expressions between tumor and normal groups across 20 types of malignancies, including THCA (P<0.001)." (PMID 39726600, 2024). "THCA tumor invasion by 24 immune cell types was assessed using ssGSEA, and their correlation with SOX13 levels was measured using Spearman’s correlation coefficients." (PMID 39726600, 2024). "Our findings suggest that decreased levels of SOX13 are closely linked to mechanisms that facilitate immune evasion in THCA tumor cells, thereby contributing to both tumor growth and progression." (PMID 39726600, 2024). "A further comparison of 59 paired THCA and normal tissues confirmed these findings, showing reduction of SOX13 in tumor tissues (P< 0.01)." (PMID 39726600, 2024). "In another cohort of patients who received cisplatin-based neoadjuvant chemotherapy (n = 52) 10, high coexpression of SOX13/SCAF1 was positively correlated with poor response to chemotherapy as evidenced by higher tumor regression grades (TRG)." (PMID 38769295, 2024). "These investigations revealed that silencing SOX13 markedly restrained the formation of tumor by modulating glycolysis." (PMID 35611828, 2022). "Inhibition of MALAT1 reduced tumor growth of MM by increasing miR-1271-5p and decreasing SOX13 in vivo, insinuating that MALAT1 contributed to tumorigenesis via the regulatory axis of miR-1271-5p/SOX13." (PMID 31953613, 2020). "As SOX13 showed differential expression between PDAC tumour and normal pancreas tissue, we decided to investigate its role in PDAC invasion and colony formation." (PMID 33424970, 2020). "SOX13 was the only gene that displayed significant differential expression between adjacent normal and tumour pancreas tissue (P value = 0.018)." (PMID 33424970, 2020). "SOX13 expression effectively distinguished between tumor and normal thyroid tissue." (PMID 39726600, 2024).
tumor (continued). "Furthermore, the data gained from xenograft tumor model illustrated that silencing SOX13 suppressed the tumor growth in nude mice and the glycolysis of tissues." (PMID 35611828, 2022). "MiR-1271-5p acted as a tumor repressor by targeting SOX13 in MM." (PMID 31953613, 2020). "The findings underscored the critical significance of the SOX13 gene in THCA prognosis and demonstrated its correlation with clinical outcomes in the THCA cohort, including tumor-invading immune cells." (PMID 39726600, 2024). "A relationship between tumor immune cells and angiogenesis in KIRC samples' data obtained from TCGA was studied, and RFX2, SOX13, and THRA were identified as the top three MTF in regulating angiogenesis signature in KIRC patients." (PMID 35096203, 2022). "Meanwhile, silencing SOX13 effectively suppressed the protein level of TRIM11, PCNA and GLUT1, indicating that SOX13 knockdown inhibited growth as well as glycolysis of tumor (**p < 0.01, *p < 0.05)." (PMID 35611828, 2022). "One of these targets, SOX13, was found to be upregulated in PDAC tumour compared with normal tissue in TCGA and an independent data set by qPCR and immunohistochemistry." (PMID 33424970, 2020). "The expression of SOX13 in PDAC tumour compared with normal pancreas was then investigated in the TCGA PDAC data set; although only a small number of normal samples (n = 4) SOX13 mRNA was significantly higher in tumour specimens compared with normal (P value = 0.015)." (PMID 33424970, 2020).
infection (1 paper, 2024). The state of being infected such as from the introduction of a foreign agent such as serum, vaccine, antigenic substance or organism. "Sires with less susceptible alleles had daughters with higher IgG levels, lower SOX13 gene expression, higher carcass weight post-infection with higher backfat thickness, and lower lean meat percentage." (PMID 39696499, 2024). "Prior to infection, piglets were screened for immunity parameters (IgG levels in plasma and SOX13 mRNA expression in blood) and genetic markers previously associated to PRRSV immune response and immunity traits." (PMID 39696499, 2024). "Plasma IgG levels and SOX13 mRNA expression levels in blood were quantified before the outbreak took place in apparently healthy animals showing no signs of infection." (PMID 39696499, 2024).
SOX13 also shares sentences with these, for which no sentence is quoted: renal clear cell carcinoma (3 papers); psoriasis (2); abdominal aortic aneurysm (1); acute myeloid leukemia (1); adenocarcinoma (1); anaplastic thyroid cancer (1); autism spectrum disorder (1); autoimmune disease (1); breast invasive carcinoma (1); cholangiocarcinoma (1); chondrodysplasia (1); Cognitive impairment (1); esophageal carcinoma (1); Hypertension (1); leukemia (1); nonsmall-cell lung cancer (1); Obesity (1); oligodendroglioma (1); osteoarthritis (1); ovarian carcinoma (1); primary biliary cirrhosis (1); rheumatoid arthritis (1); schizophrenia (1).